GSK3B (glycogen synthase kinase 3 beta)
Diseases named in the same sentence as GSK3B in open-access papers (continued):
Sharing a sentence is not in itself a finding about the gene and the disease.
tumor (continued). "have reported that energy sensor AMPK was markedly reduced in tumour‐infiltrating Tregs, which can enhance the PD‐1 expression of Tregs via the HMGCR/p38 MAPK/GSK3β signalling axis and further suppress tumour progression in an LKB1‐independent manner." (PMID 40045458, 2025). "This activation promotes the phosphorylation of GSK3β, which suppresses the expression of programmed cell death protein 1 (PD-1), thereby enhancing the anti-tumor activity of T cells." (PMID 41450917, 2025). "E-cadherin functions as a tumor suppressor protein, and its downregulation facilitates EMT and induces tumor metastasis by suppressing GSK3β-mediated β-catenin phosphorylation and upregulating Twist, an EMT transcription factor." (PMID 40657637, 2025). "From a precision oncology standpoint, identifying tumor genotypes that predict responsiveness to GSK3β-PARPi combinations will address an important unmet clinical need." (PMID 41243967, 2025). "On the other hand, different roles of GSK-3β as an anticancer and tumor-development promoting agent have been reported so far; therefore, applying drugs targeting GSK-3β in cancer treatment seems controversial." (PMID 40649990, 2025). "The dual nature of GSK3β, its capability of being both an oncogene and a tumor suppressor, enables it to behave differently in different types of cancer." (PMID 41465855, 2025). "The expression of GSK3B was positively correlated with tumor purity, infiltration abundance of B Cell, CD8 + T Cell, Macrophage and Neutrophil." (PMID 41287122, 2025). "Lastly, overcoming PARPi resistance through pharmacological targeting the GSK3B-53BP1 axis requires functional 53BP1 in tumor cells." (PMID 41243969, 2025). "Stabilization of PD-L1 by inactivation of GSK3β or inhibiting β-TrCP enhances tumor-immunosuppressive function and gives an advantage for tumor cell survival in an in vivo mouse model." (PMID 40087690, 2025). "For instance, GABA signaling—typically associated with neuronal function—has been shown to inhibit GSK-3β activity via GABAB receptor activation, thereby enhancing β-catenin signaling-mediated tumor growth and immune suppression." (PMID 41373475, 2025). "Ultimately, inhibition of GSK3β upregulates the expression of PD-L1 in tumor cells that facilitating tumor immune escape." (PMID 40701777, 2025). "The inhibitory role of GSK-3β in EndMT was demonstrated using a tumor spheroid model containing lung cancer cells and HUVECs." (PMID 40650130, 2025). "Our study highlights the role of Glycogen Synthase Kinase 3β (GSK3β) in regulating Notch signaling in response to stress hormones in OC, inducing tumor cell proliferation." (PMID 41488655, 2025). "CDK12 directly interacts with and regulates GSK3β, which in turn influences tumor metabolism and growth." (PMID 40996961, 2025). "Inhibition of GSK3B can lead to sustained TGF-β1 signaling, promoting EMT, a process associated with tumor progression and metastasis." (PMID 40943648, 2025). "ILK1 induces the production of vascular endothelial growth factor through downstream effector molecules such as GSK‐3β, which plays a regulatory role in tumour growth." (PMID 39343985, 2025). "For example, GSK3β promotes the transcriptional activity of NF-κB through the IκB kinase complex, thereby maintaining the NF-κB-mediated tumor survival pathway." (PMID 39762409, 2025). "We aim to explore the expression of proteins upstream and downstream of GSK3β, to understand better its role in inducing tumor apoptosis and inhibiting metastasis." (PMID 40495167, 2025). "Triptolide has been shown to suppress the GSK-3β phosphorylation, which in turn slows tumor growth and reverses EMT in Taxol-resistant LUAC." (PMID 41217667, 2025).
tumor (continued). "In NHL and HCC, SIRT3 deacetylates and activates GSK‐3β, inducing the expression and mitochondrial translocation of the proapoptotic protein Bax and triggering mitochondrial apoptosis, thereby inhibiting tumour growth." (PMID 39778006, 2025). "GNE-6776 significantly inhibited tumor growth without affecting body weight, reduced expression of CDK6, C-myc, and N-cadherin, and increased GSK3β expression in tumor tissue." (PMID 40006058, 2025). "In summary, we report a significant mechanism whereby PPI usage directly induces PD‐L1 expression by stimulating GSK3β phosphorylation, thus facilitating primary tumor progression and metastasis." (PMID 38752436, 2024). "We further investigated the set of genes undergoing A/B compartment switches within the PI3K‐Akt signalling pathway and found that the GSK3B gene region switched from compartment B in normal tissue to compartment A in somatotroph tumours." (PMID 38769659, 2024). "GSK-3β promotes tumor cell growth and facilitates EMT by influencing DNA damage repair, making breast tumor cells resistant to chemotherapy and targeted therapies." (PMID 39769140, 2024). "GSKIP acts as a negative regulator of GSK3β in the Wnt signaling pathway, influencing vital cellular processes like differentiation, proliferation, and tumor formation." (PMID 39192051, 2024). "After treating GSK3β‐KO tumor cells with PPIs and then detected the expression of PD‐L1 on tumor cell membrane, we found that OME and ESO were ineffective in promoting membranous expression of PD‐L1." (PMID 38752436, 2024). "miRNAs and lncRNAs: Modulate the PI3K/AKT/GSK-3β pathway by targeting key components and influencing gene expression related to tumor growth and resistance." (PMID 39156976, 2024). "GSK3β also facilitates the invasion of tumor cells and makes them unresponsive or resistant to chemotherapy and ionizing radiation." (PMID 38318525, 2024). "Inhibiting GSK-3β has been shown to lead to significant metabolic changes in tumor cells, such as a reduction in aerobic glycolysis." (PMID 39156976, 2024). "GSK3β belongs to the serine/threonine kinase family and is involved in tumor development and drug resistance." (PMID 39227379, 2024). "TUBB4A-KO reduces the MYH9-mediated ubiquitination and degradation of GSK3β, which in turn inhibits cyclin D1, acting to reduce spontaneous tumor growth and metastasis." (PMID 37847340, 2024). "GSK3β serves as a versatile serine/threonine protein kinase, wielding a pivotal influence on the transcription, proliferation, and apoptosis of tumor cells." (PMID 38720781, 2024). "Mechanistically, on the one hand, PDGF-BB activates the GSK3β and P65 pathways of tumor cells to enhance their transendothelial migration and malignancy." (PMID 37307823, 2024). "GSK3B affects cancer cell proliferation, differentiation, and apoptosis and participates in tumor development." (PMID 39166606, 2024). "These pathways involve the dual inhibition of PI3K-AKT and CDK2-Rb, along with the inactivation of GSK3β, which regulates reduced cell proliferation and increased cell apoptosis, thus impeding tumor growth." (PMID 38755637, 2024). "Secondly, compensatory function by axin (another component of the β-catenin/GSK-3β/APC/axin complex) with tumor suppressor activity has already been confirmed." (PMID 38903727, 2024). "6-Bromoindirubin-3′-Oxime (BIO) enhances the transcriptional activity of β-catenin by inhibiting the activity of GSK-3β, thereby affecting multiple signaling pathways and inhibiting the proliferation, survival, and migration of tumor cells." (PMID 39408717, 2024). "As GSK3β synergizes with its downstream β-catenin to regulate tumor cell proliferation, we investigated the effect of OMA1 depletion and overexpression on GSK3β and β-catenin expression in OS cells." (PMID 39487118, 2024). "Next, we validated the correlation between PDGFR-β expression and GSK3β and P65 signaling in normal and paired tumor tissues from patients with CCA with different node statuses." (PMID 37307823, 2024).
tumor (continued). "This discovery reveals the critical role of GSK-3β palmitoylation modification in the regulation of tumor stem cells, providing a new theoretical basis for understanding and intervening in tumor development." (PMID 39563863, 2024). "PPIs increase the translocation of PD‐L1 onto tumor cell membrane by inducing GSK3β phosphorylation." (PMID 38752436, 2024). "GSK-3b is a vital element of the β-catenin degradation complex, and its phosphorylation inactivates this complex in tumor cells." (PMID 39768811, 2024). "Apart from its initial discovery in regulating the activity of glycogen synthase (GS), GSK-3β also influences the structure and function of various signaling proteins and transcription factors, contributing to tumor formation and progression." (PMID 39563863, 2024). "In vivo experiments show similar results, bufalin can inhibit tumor growth in mice with orthotopic transplantation tumor models of HCC through the Akt/GSK3β/β-catenin/E-cadherin pathway, promoting tumor necrosis." (PMID 38803433, 2024). "Tumor cell survival is sustained by GSK3b in many cancer types, such as pancreatic, non-small-cell lung carcinoma, renal cell carcinoma, and chronic lymphocytic leukemia B cells." (PMID 38892035, 2024). "This regulation of PD-L1 stability by GSK3β represents an important mechanism controlling immune checkpoint activation in the tumor microenvironment." (PMID 38995006, 2024). "Conversely, treatment of MYCN tumor cells with the GSK3β inhibitor CHIR99021 (WNT activator) increased periostin." (PMID 38451815, 2024). "GSK-3β is an evolutionarily conserved serine/threonine kinase that plays a regulatory role in apoptosis, cell cycle, DNA repair, tumor growth, invasion and metastasis." (PMID 38969831, 2024). "The GSK3β/β-catenin signaling pathway regulates tumor cell proliferation as well as tumor cell migration and invasion under various circumstances." (PMID 39487118, 2024). "GSK-3β, in particular, has been identified as both a prognostic indicator in clinical treatment and a target for suppressing tumor growth and metastasis." (PMID 39156976, 2024). "The activation of IGF1Rβ associated with the HSPA1L/ITGAV complex enhances the tumor stemness and radiotherapy resistance of non-small cell lung cancer through downstream AKT/NF-κB or AKT/GSK3β/β-catenin activation pathways." (PMID 39239559, 2024). "By screening the classical downstream signaling pathway of PDGF-BB, we found that PDGF-BB mainly activated the GSK3β and P65 signaling pathways in tumor cells." (PMID 37307823, 2024). "Here, we investigated the function of GSK3B in HeLa cell tumorigenesis and in vivo xenograft tumor growth by gene silencing or chemical inhibition." (PMID 39166606, 2024). "GSK3β is widely recognized as a downstream target of AKT 20, and previous studies have shown that inhibition of ASPH enzymatic activity leads to increased GSK3β phosphorylation, which promotes tumor cell senescence 21,22." (PMID 38817852, 2024). "PARP inhibitors can also inactivate GSK3β to increase PD-L1 expression in tumor cells, and combination with PD-L1 inhibitors can enhance the antitumor efficacy of PARP inhibitors." (PMID 38869633, 2024). "We also discuss the involvement of GSK3β in the formation of desmoplastic tumor stroma and in promoting anti-cancer immune evasion, both of which constitute major obstacles to successful cancer treatment." (PMID 38318525, 2024). "Studies have revealed that both inhibition and activation of GSK-3β can significantly impact tumor initiation and progression." (PMID 39156976, 2024).
tumor (continued). "Delivery of exosomal miR-1246 targets GSK3β and promotes β-catenin nuclear accumulation, suggesting a deregulation of the Wnt pathway, known to be important in tumor progression." (PMID 38730605, 2024). "This novel DNMTI-specific DNA hypomethylation pattern triggers dual inhibition of PI3K-AKT and CDK2-Rb and inactivation of GSK3β, leading to enhanced tumor regression in comparison to that of a PI3K inhibitor." (PMID 38755637, 2024). "Unexpectedly, CD11c-GSK-3β−/− mice exhibited significantly slower tumor growth, leading to substantially smaller tumor sizes compared to WT mice." (PMID 39340067, 2024). "Consistent with our data, 9‐ING‐41, a small molecule inhibitor of GSK‐3β, has demonstrated anti‐tumor activity in patient‐derived xenograft mice (PDX) of various human cancers including PDAC by inhibiting the NF‐κB target genes such as BCL‐2." (PMID 39632551, 2024). "HCV core protein can reduce E-cadherin expression levels due to CDH1 gene promoter hypermethylation, with consequent dissociation of the β-catenin/E-cadherin complex, and stimulates tumor cell growth by GSK-3β inactivation and Wnt3a release." (PMID 37512809, 2023). "ATL I and II modulate the cancer cell cycle through the PI3K/Akt and ERK/GSK3β signaling pathways, resulting in apoptosis and anti-tumor effects." (PMID 37241729, 2023). "Though the inhibition of GSK3β (increase in p-GSK3β-ser9) is a common feature seen in many cancers, inhibiting GSK3β activity can also be tumor-suppressive and can reduce the migration and invasion of cancers." (PMID 38213538, 2023). "Glycogen synthase kinase 3β (GSK-3β) is an active proline-directed serine/threonine kinase, which is closely related to tumor formation and progression." (PMID 36874032, 2023). "It has been proven that aripiprazole down-regulates the proportion of cancer stem cells in tumor cells by inhibiting the Wnt/GSK3β/β-catenin pathway." (PMID 37649087, 2023). "Recent studies have shown that dual HDAC/GSK3β inhibition therapy promotes neuronal survival and controls tumor growth." (PMID 37443080, 2023). "GSK-3β has important roles as both a tumor suppressor (e.g., inhibition of β-catenin, c-Myc, and Mcl-1) and promoter (e.g., inhibition of the cell cycle inhibitor p27Kip1)." (PMID 36674871, 2023). "Published studies have shown that the PI3K/AKT/GSK-3β pathway played an important role in the process of tumor cells migration, invasion, and apoptosis." (PMID 37899170, 2023). "Administration of GSK3β inhibitors showed to suppress cell proliferation and inhibit tumour formation in mice." (PMID 37055381, 2023). "Alternatively, a predominantly tumor-suppressive role for GSK3B is observed in MB, in which its accumulation leads to the downregulation of GLI, the most important activator and driver of the SHH medulloblastoma subtype." (PMID 36839989, 2023). "In tumours, GSK-3β has been demonstrated to play a paradoxical role as GSK-3β acts as a tumour promoter or suppressor based on the cell type and phosphorylation status." (PMID 38107562, 2023). "As a core downstream component of PI3K/Akt, GSK3β mediates many biological processes in tumor cells and promotes the development and metastasis of many types of tumors through EMT." (PMID 37608369, 2023). "More importantly, we provide evidence that CD58 and sCD58 exert their pro-tumor effects by activating the AKT/GSK-3β/β-Catenin pathway." (PMID 37573318, 2023). "GSK3B is an effector downstream of ErbB signaling that plays an important role in tumor proliferation by directly regulating P21 and Cyclin D1." (PMID 38017514, 2023). "GSK3B (K85) was identified in two tumor samples from patients with LNM, suggesting its overactivation, which is in contrast to a prior study." (PMID 36520032, 2023).
tumor (continued). "GSK3β, therefore, plays multifunctional roles in the immune tumor microenvironment, an unsurprising result due to the diversity of the GSK3β substrate." (PMID 36672256, 2023). "GSK3β, a serine/threonine protein kinase, can act as a tumor suppressor or tumor promoter depending on the types of cancer cells." (PMID 37259304, 2023). "Further study demonstrated that CD58 and sCD58 exert their pro-tumor effects by activating the AKT/GSK-3β/β-Catenin pathway." (PMID 37573318, 2023). "Expression levels of β-catenin and its downstream targets were significantly reduced, while GSK-3β levels were noticeably increased in PDX-derived tumor cells subjected to ACTN1 depletion." (PMID 38057867, 2023). "In the D5 (DAC stage), mTOR signaling (e.g., AKT2 and RPTOR) and EGFR signaling (e.g., EGFR and GSK3B) were overrepresented, implying the progression of cancer and tumor growth." (PMID 36991000, 2023). "AXL tyrosine kinase promotes tumor progression through AKT/GSK-3β/β-catenin signaling, β-catenin nuclear-translocation-induced SNAIL transcription, and MMP-2 and MMP-9 activation." (PMID 37046676, 2023). "The PI3K inhibitor, wortmannin, considerably prevented the phosphorylation of Akt and GSK-3β, which subsequently diminished the nuclear localization of β-catenin and therefore accelerated the tumor-inhibiting effect of DIM and 5-Fu." (PMID 36785670, 2023). "Collagen VI can directly affect tumor cells and increase tumorigenesis by activating the Akt – GSK-3b – β-catenin – TCF/LEF pathway and positively regulating transcription factors (TFs), protein kinases, angiogenic factors, and growth factors." (PMID 37361568, 2023). "The AKT/GSK-3β/β-catenin pathway is involved in a number of hallmarks of cancer, such as tumor grade and lympho-node metastasis." (PMID 36925651, 2023). "Our study found that kumatakenin and BDMC have huge potential as GSK3β inhibitors, exhibiting effective inhibition of tumor cell growth." (PMID 37608369, 2023). "Regarding GSK3β, its role in cancer is contradictory: The enzyme functions as a tumor promoter or suppressor based on the context, cell type, and phosphorylation status." (PMID 37371884, 2023). "Other protein kinases that are enriched in TAMs of HCC tumours based on single-cell RNA sequencing data include glycogen synthase kinase 3β (GSK3β)." (PMID 37894344, 2023). "We suggest that LTB4R2 activation by 12-HHTrE produced by aHSC CYP1B1 causes CTNNB1 activation via GSK3β pathway and subsequent YAP1 transcription and tumor promotion." (PMID 37156770, 2023). "The TNM plots revealed a high expression of c-Met/GSK3β/MYC/CCND1 in tumor tissues compared to normal colon tissues." (PMID 36672275, 2023). "This was also supported by IHC staining for the phosphorylation of Akt at T308 and Gsk3β at S9 in tumor tissues of Brafm/+; Tet1−/− and Brafm/+; Tet1+/+ mice." (PMID 37020036, 2023). "For example, GSK3β regulates multiple cellular processes and has both tumour-suppressing and tumour-activating functions, making its role in tumour development unclear." (PMID 36670508, 2023). "AXL tyrosine kinase promotes tumor progression through serine/threonine protein kinase (AKT)/GSK-3β/β-catenin signaling, β-catenin nuclear-translocation-induced snail family transcriptional repressor 1 (SNAIL) transcription, and activation of MMP-2 and MMP-9." (PMID 37046676, 2023). "The PI3K/AKT/GSK-3β signaling pathway is one of the main pathways involved in the regulation of tumor cell EMT." (PMID 37899170, 2023). "The AKT/GSK-3β/β-catenin cascade is a key pathway involved in the survival, growth, and metabolic stability of tumor cells." (PMID 36925651, 2023).